IDO1 (indoleamine 2,3-dioxygenase 1)
Diseases named in the same sentence as IDO1 in open-access papers (continued):
Sharing a sentence is not in itself a finding about the gene and the disease.
tumor (continued). "Again, the authors showed that IFN-γ treatment resulted in IDO1/AhR-dependent p27 induction, that prevented STAT1 signaling, suppressing cell death and inducing tumor cell-dormancy in murine TRCs." (PMID 32296435, 2020). "BCPN released OXA and NLG919 in the acidic and reductant tumor microenvironment to promote ICD induction and IDO-1 inactivation." (PMID 32317755, 2020). "Other new IDO1 inhibitors have emerged, such as BMS-985205, PF-06850003, and navoximod, being investigated in preclinical and clinical research for different tumor types." (PMID 32469935, 2020). "By analyzing tumor samples from patients treated with the PD1 antagonist Pembrolizumab, we observed a high level of IDO1 expression." (PMID 32194552, 2020). "The increased IDO1 activation decreases intratumoral TRP levels, resulting in tumor starvation and increase in kynurenine (KYN) metabolites (which are toxic to lymphocytes)." (PMID 32117235, 2020). "Nevertheless, they provide rationale for studying PD-1 and IDO-1 inhibitors in combination with standard chemotherapy for patients with high PD-L1+ and IDO-1+ TAM content in their tumor tissue." (PMID 32260340, 2020). "Within the tumor microenvironment, MDSC were also identified as the primary source of PGE2 and IDO1." (PMID 33260925, 2020). "Upregulation of IDO1 in MDSC and tumor cells leads to Trp depletion that impairs cytotoxic T cell responses and survival." (PMID 32391020, 2020). "We further validated the correlation of IDO1/CD8A stratification and cancer progression, and investigated tumor immune status through an in vivo model." (PMID 33425745, 2020). "However, its role in female tumours lacks a detailed report, so we aimed to provide some new insights into understanding of IDO1 in the regulatory mechanism of female tumours and suggest that IDO1 may be a potential therapy target for female." (PMID 32227579, 2020). "Moreover, other studies showed that IDO1 was also expressed in various non‐tumour cells in the tumour microenvironment, such as dendritic cells, fibroblasts, endothelial cells, eosinophils and macrophages which may increase the contradictory role of IDO1 with clinical outcome." (PMID 32227579, 2020). "Tumor IDO1 expression and CD8+TILs within TME in paired specimens were evaluated by immunohistochemistry, and the changes of tumor IDO1 expression and CD8+TILs between the paired specimens were estimated." (PMID 32733806, 2020). "Expression of IDO1 is induced by IFN-γ, which coordinates a cascade of events to combat pathogens and neoplasia." (PMID 33261077, 2020). "At the tumor microenvironment, TRP catabolism is promoted by indoleamine 2,3-dioxygenase (IDO1) overexpression under pro-inflammatory conditions, and it plays an important role in modulating antitumor immune response." (PMID 33178611, 2020). "When the diameter of the tumor reaches 5 mm, GBP1 and IDO1 knock-down lentivirus were used for intertumoral injection." (PMID 33552086, 2020). "Our experiments well clarified a reciprocal positive regulation between IDO1 and COL12A1 to promote tumor metastasis, which was mediated by IDO1 metabolite kynurenine and integrin β1." (PMID 31315643, 2019). "By IHC staining, we examined IDO1, COL12A1 and phosphorylation ERK expression in primary tumor of the four groups." (PMID 31315643, 2019). "Some other strategies to boost CAR T cell function in the TME include inhibiting suppressive soluble factors, like adenosine, IDO1, and VEGF, and protecting against the immune suppression of non-tumor cells in the TME like MDSCs, TAMs, and stromal cells." (PMID 30804938, 2019). "This process is accompanied by enhanced TGF-β signaling in local DC populations, resulting in IDO1 upregulation in pDCs and CCL22 production in cDCs, both resulting in the accumulation of Tregs and the suppression of anti-tumor immunity." (PMID 31921140, 2019).
tumor (continued). "Hypothetically, the IFN-γ-STAT1 signaling induces apoptosis in proliferating tumor cells; however, TRCs-induced overexpression of IDO1 and AhR, shifts IFN-γ action and give rise to IDO1/AhR-induced p27 activation and inhibition of STAT1 signaling." (PMID 31430951, 2019). "It is worth noting that, while initiating the immune response against NY-ESO-1+ tumor cells as a tumor antigen, NY-ESO-1 is able to regulate an immuno-suppressive TME by inducing IDO1 production and Tregs." (PMID 31771653, 2019). "Tryptophan degradation by IDO1/2 or TDO limits innate and adaptive immune responses by depleting the tumor local microenvironment of trytophan and by promoting the accumulation of kynurenine resulting from catabolism of tryptophan." (PMID 30728077, 2019). "A potential explanation for this unfavourable outcome is the expression of both IDO1 and TDO2 in the patients’ tumours." (PMID 31795096, 2019). "miR-448, as a tumor-suppressive miRNA, enhanced the CD8+ T cell response by inhibiting IDO1 expression." (PMID 31391111, 2019). "IDO1 is ubiquitously expressed by components of the TME, including tumor cells, stromal cells, DCs, and MDSCs." (PMID 31681327, 2019). "Cancers often express high levels of IDO1 and/or TDO and TRP metabolism represents a critical metabolic pathway controlling tumor immune evasion as well as tumor cell malignant properties." (PMID 31612110, 2019). "Because miR-448 downregulated IDO1 protein expression and suppressed IDO1 function by targeting IDO1, and the IHC results strongly suggested that IDO1 modulated tumor CD8+ T cell immunity, it is rational to hypothesize that miR-448 can affect the CD8+ T cell response by suppressing IDO1 expression." (PMID 31391111, 2019). "High IDO1 levels suppress the CD8+ T cell response in these patients, resulting in tumor immune escape." (PMID 31391111, 2019). "OXA induced adaptive antitumor immunogenicity by triggering immunogenic cell death of the tumor cell, while NLG919 inactivated IDO-1, thereby inhibiting intratumoral infiltration of T-regs." (PMID 30871158, 2019). "At this respect, enhanced expression of arginase 1 (ARG1) and indoleamine 2,3-dioxygenase 1 (IDO1), enzymes that catalyze the degradation of arginine and tryptophan, respectively, have been documented in tumor infiltrating DCs and MDSCs." (PMID 31535086, 2019). "The tumour samples were stained for inducible nitric oxide synthase (iNOS, M1 marker), CD163 (M2 marker), FoxP3 (Treg marker), CD47 and IDO1." (PMID 31358801, 2019). "Eight potential classifiers were studied including CR, clinical stage of tumor at the time of diagnosis, CD8 density, PDL-1 status, CXCL9, IDO1, LAG3, and TIM3." (PMID 31360303, 2019). "The IDO1 small molecule inhibitor navoximod (GDC-0919, NLG-919) is active as a combination therapy in multiple tumor models." (PMID 29921320, 2018). "IDO1 is under genetic control of the cancer-suppression gene bridging integrator 1 (Bin1), and Bin1 knockout results in tumor growth and immune suppression in mice by upregulating STAT1- and NF-κB-dependent expression of IDO1." (PMID 30068361, 2018). "Preclinical and clinical studies suggest that the immune effects of tumor-directed vaccine, PD-L1 blockade, TGF-β sequestration, IL-15 agonism, and IDO1 inhibition can be additive and/or synergistic." (PMID 30227893, 2018). "Previous studies have found that IDO1 peptides elicit specific CD8+ T cells that recognize and kill IDO1-expressing tumor cells and DCs and simultaneously enhance other T-cell responses." (PMID 30068361, 2018). "In addition, TGF-β and other immunosuppressive molecules produced by tumor cells may recruit and activate immune cells including Tregs, MDSCs, CD11b+Ly6G+ neutrophils, and indoleamine 2,3-dioxygenase 1 (IDO1)-expressing DCs that further suppress NK cell activity." (PMID 30597841, 2018).
tumor (continued). "In preclinical combination studies with anti-PD-L1 and anti-OX40, inhibition of IDO1 showed greater effect in activating intratumoral CD8+ T cells and inhibiting tumor growth than either treatment alone." (PMID 29921320, 2018). "In AML, the trends for CD276, IDO1, and NKG7 all have substantially different intercepts and slopes than seen in the other tumor types." (PMID 29929551, 2018). "Among the three IDO enzymes catabolizing tryptophan, IDO1 expression is limited in normal human tissues but is high in tumor tissues, making it an ideal target for cancer therapy." (PMID 29685162, 2018). "These were evaluated in induced HeLa tumor bearing mice wherein IDO1 was induced with IFN-γ and showed high correlation with IDO1 expression and [18F]IDO49 tracer uptake." (PMID 28159919, 2017). "A murine HeLa tumor model with IFN- γ treatment, enabled us to confirm the [18F]IDO49 accumulation in IDO1 positive tumors." (PMID 28159919, 2017). "IDO has two isoforms, IDO1 and the recently discovered IDO2, both are expressed in tumors and tumor-draining lymph nodes." (PMID 28159919, 2017). "IDO1 and TDO2 are involved in catabolism of tryptophan (trp) which depletion in tumor microenvironment results in inhibition of T cell responses." (PMID 29285252, 2017). "In correlation with this finding, IDO1 inhibitor increased CD8+ T cells and reduced tumor growth in a transgenic mouse model of cecal gastrointestinal stromal tumors, which was reversed by CD8+ T cell depletion." (PMID 28191010, 2017). "We assessed the uptake of these tracers in vitro in IDO1 expressing tumor cell lines and also evaluated [18F]IDO49 in IDO1-expressing tumor models using microPET." (PMID 28159919, 2017). "Here, we report radiofluorinated carboximidamides based on the IDO1 inhibitor, INCB024360, as IDO1 targeted tracers for tumor imaging with PET." (PMID 28159919, 2017). "However, the precise mechanisms regulating tumoral IDO1 expression in tumor milieus remain unclear." (PMID 26895379, 2016). "Some factors have been reported that give tumor cells the ability to escape from host immunity, including interferon-γ (IFN-γ), galectin, transforming growth factor β (TGF-β), and indoleamine 2, 3-dioxygenase 1 (IDO1)." (PMID 26517244, 2016). "IDO1 and TDO2 play important roles in mediating both tumor immunoescape and immune response regulation." (PMID 27578919, 2016). "Like IDO1, IDO2 is an immunosuppressive molecule, and it plays an important role in induction and maintenance of tumor microenvironment immune tolerance." (PMID 27058624, 2016). "Knocking down IDO1 using siRNA-reduced NAD+ generation, leads to enhanced sensitivity of tumor cells to chemotherapeutic drugs." (PMID 27058624, 2016). "Further, the correlation between IDO1 and TDO2 expression in the tumor tissues of the CRC patients was analyzed." (PMID 27578919, 2016). "Taken together, our data supported the notion that IDO1 expression in tumor cells might serve as a counter-regulatory mechanism regulated by immune system, and provided new insights into the collaborative action of different inflammatory cells in tumor immunosuppression." (PMID 26895379, 2016). "Indoleamine-2,3-dioxygenase-1 (IDO1) is an intracellular immunoregulatory enzyme that contributes to immunosuppression, tolerance and tumor escape by catabolizing tryptophan." (PMID 27192116, 2016). "A possible mediator of IDO1-dependent Treg expansion is the increase of chemokines like CCL2 which attracts Treg cells, leading to a global tumor immune tolerance." (PMID 27174915, 2016). "Accordingly, active expansion of Tregs cells through KYN-AhR activation creates an immune suppressive zone around IDO1 and/or TDO2 expressing tumours." (PMID 26646699, 2016). "Collectively, these studies highlight the importance of the AhR in IDO1 and/or TDO2 expressing tumours and emphasize the role that autocrine production of inflammatory cytokines plays in tumour survival and growth." (PMID 26646699, 2016).
tumor (continued). "Further, a significant correlation was detected between high levels of IDO1 expression and reduced numbers of CD3+, CD8+ and CD57+ cells infiltrating both the tumor epithelium and stroma." (PMID 26378585, 2015). "IDO2 has even been found to be expressed in human tumor cells, but the physiologically significant degradation of TRP to KYN is catalyzed by IDO1." (PMID 26881062, 2015). "Loss of Bin1 in tumors results in transcriptional upregulation of IDO1 via STAT1 and nuclear factor (NF)-kB and subsequent escape from T cell-dependent anti-tumor immunity." (PMID 25628622, 2014). "Contributing to the poor success of past approaches is the expression of indoleamine 2,3-dioxygenase 1 (IDO), a tryptophan catabolizing enzyme overexpressed in GBM, and critically involved in regulating tumor-infiltrating Treg levels." (PMID 23720663, 2013). "Higher IDO1 expression at the tumour invasion front is involved in CRC progression and correlates with impaired clinical outcome, suggesting that IDO1 is an independent prognostic indicator for CRC." (PMID 22108515, 2012). "Another research group could not confirm the correlation between IDO1 expression in CRC cells and survival, but these authors demonstrated that high density of IDO1-expressing cells in tumour-draining lymph nodes without metastasis was associated with a lower survival rate." (PMID 22108515, 2012). "Recently a novel IDO isoform, termed IDO2 was discovered, which - like IDO1 - is expressed in tumors and tumor-draining lymph nodes." (PMID 21625531, 2011). "Consequently, in tumor cells with upregulated PRMT3, IDO1 transcription is enhanced, thereby activating Kyn metabolism." (PMID 41129671, 2026). "IDO1 inhibitors reduce KYN and T cell exhaustion, restoring anti-tumor immune responses." (PMID 41602107, 2026). "In vitro assays confirmed that endothelial cells were educated by SLC1A3hi tumor cells that undergo malignant transition, drastically upregulating immune-suppressive factors, including CD274, TGFB1, IL10, and IDO1." (PMID 42112375, 2026). "Analysis of tumor tissue sections from patients with NSCLC and mouse models demonstrated a significant positive correlation between PRMT3 and IDO1 expression levels." (PMID 41129671, 2026). "For amino acid metabolism, studies have found that chemotherapy can upregulate the expression of tryptophan metabolism enzyme IDO1 and tryptophan transporter SLC7A5, which enhances the tumor uptake of tryptophan and its metabolism to the downstream product kynurenine (Kyn)." (PMID 41281744, 2025). "Meanwhile, the non-enzymatic conformation of IDO1 inside the tumor cells still continues to trigger an unexpected pro-tumorigenic signaling, resulting in faster proliferation and migration of the tumor exposed to catalytic inhibitors." (PMID 41262240, 2025). "GBM cells typically do not express IDO1, but it is inducible by interferons secreted by tumor-infiltrating T cells." (PMID 39863603, 2025). "In GBM mouse models, IDO1 expression in nonmalignant cells also promoted tumor progression, suggesting that the combined use of IDO1 inhibitors with radiotherapy and immunotherapy can improve treatment efficacy." (PMID 40800581, 2025). "Since cellular dormancy requires high signaling, the low expression of IDO1 and AhR in tumor cells fails to generate sufficient p27 and other dormancy‐related proteins, leading to a different response to IFN‐γ." (PMID 40103267, 2025). "Likewise, an oxaliplatin–phthalocyanine coordination polymer combined with an IDO1 inhibitor prodrug forms a laser- and GSH-activatable nanosystem that promotes deep tumor penetration and restores antitumor immunity." (PMID 40520550, 2025). "In the early setting, immune cell subpopulations (CD8 T cells, cytotoxic cells, macrophages), soluble mediators (IFN-γ, inflammatory chemokines), other immune checkpoint expression levels (PD-L2, IDO1, TIGIT), and tumor inflammation signature correlated with pCR in the GIADA trial." (PMID 40941037, 2025).
tumor (continued). "In this study, we found that the mRNA expression levels of IDO1 were higher than those of TMIGD2 in nearly all patients, indicating that both the activation of inhibitory immune pathways and the weakening of stimulatory pathways promote tumor immune evasion." (PMID 40061889, 2025). "Additionally, IDO1-expressing Paneth cells, influenced by STAT1 in colorectal cancer, can promote immune escape by modulating the tumor load through immune cell infiltration." (PMID 40909948, 2025). "The results revealed markedly increased IDO1 expression in GBM specimens compared to that in adjacent non-tumor tissues." (PMID 39863603, 2025). "Unlike the immune suppression observed in tumor microenvironments, IDO1 upregulation in the pro‐inflammatory environment of these inflammatory diseases does not significantly reduce inflammation, possibly due to KYUN expression." (PMID 40103267, 2025). "Based on the relevance of high IDO1 and TDO2 expression in many tumours and their poor prognosis, and the role of many products of the KP metabolic in driving tumour development, we believe it is reasonable to explore IDO inhibitors, TDO2 inhibitors and dual IDO1/TDO2 inhibitors." (PMID 40040508, 2025). "Inhibiting GBP1 may overcome resistance in cancers such as ovarian and lung, where sh-GBP1 inhibits tumor growth and restores erlotinib sensitivity by disrupting EMT signaling and IDO-1 interactions." (PMID 40564939, 2025). "Both IDO1 and IL4I1 were expressed by HNSCC tumor cells in the TMA." (PMID 40332319, 2025). "Concentrations of mRNA and protein for the tumor cell promotor and inflammation mediator IL-6 and immunosuppressor and tumor promotor IDO1 were determined in MSC medium supernatants with and without cisplatin treatment." (PMID 40699630, 2025). "Initially, GBM expression of IDO1 was thought to positively correlate with tumor grade mediated by the metabolic effects of IDO1; however, recent work has also uncovered non-metabolic IDO1-driven pro-tumoral effects." (PMID 40507361, 2025). "In contrast, the HMP1G NPs group showed abundant CD8+ T cell infiltration in the field of view with minimal levels of IDO1 and KYN, suggesting a significant improvement in the metabolic and immunosuppressive states within the tumor microenvironment following HMP1G NPs treatment." (PMID 39661740, 2025). "Overall, our recent observations in tumor cells indicated a pro-tumorigenic adverse effect of IDO1 catalytic inhibition attributable to the non-enzymatic (i.e., signaling) function of IDO1 in tumor cells." (PMID 41262240, 2025). "Ideally, we will translate these preliminary findings into an in vivo model to confirm that non-enzymatic IDO1 plays a significant role in tumor survival mechanisms." (PMID 41262240, 2025). "Differently, IDO1’s non-enzymatic activity in tumor cells activates a pro-tumorigenic signaling, enabling tumor proliferation." (PMID 41262240, 2025). "They stabilize the non-enzymatic conformation of IDO1, making it more prone to associate with the oncogene SHP-2 and to trigger an intracellular signaling pathway within the tumor cells." (PMID 41262240, 2025). "This combination therapy may also reshape the TME by reducing the secretion of immunosuppressive and tumor-promoting metabolites such as lactate and kynurenine, as a consequence of LDH and IDO1 inhibition, respectively." (PMID 40550880, 2025). "In the presence of an IDO1 inhibitor, tryptophan levels can be increased and the accumulation can induce tumor regression by upregulating the production of IL-12 and IFN-γ cytokines and T cells and neutrophils in mouse metastastic liver and blade tumor models." (PMID 40092297, 2025). "Additionally, we treated tumor cells with the ferroptosis activator erastin and observed that erastin significantly increased KYNU expression while suppressing IDO1 expression; in contrast, the ferroptosis inhibitor Ferrostatin-1 produced the opposite result." (PMID 40365295, 2025).